ATR (ATR checkpoint kinase)
Diseases named in the same sentence as ATR in open-access papers (continued):
Sharing a sentence is not in itself a finding about the gene and the disease.
tumor (continued). "Therefore, targeting key enzymes involved in DNA DSB repair, particularly the protein kinases ATM, ATR and DNA-Pkcs, in relatively radioresistant HPV-negative HNSCC that are DSB repair-proficient is considered to be an approach to sensitise these tumours to radiotherapy." (PMID 32517381, 2020). "One study demonstrated that the ATR inhibitor AZD6738 induces a synthetic lethal phenotype in ATM‐deficient, but not ATM‐proficient, gastric cancer cells, and in vivo tumor growth of ATM‐deficient gastric cell xenografts was effectively controlled by treatment with AZD6738 compared with control." (PMID 30714316, 2019). "Molecular studies further determined that enforced miR-184 plays tumor-suppressive roles in RB cells and enhances chemosensitivity via enhancing G2/M phase arrest and cellular apoptosis mediated through directly targeting SLC7A5 and its downstream ATR/ATM pathway." (PMID 31803607, 2019). "Whilst it is not clear whether conditions such as BPES-ATR+/-, MDLS and WBS represent tumour-predisposition conditions, it is clear that they do exhibit a defective ATR-dependent DDR." (PMID 19440510, 2008). "Thus, tumours with ATM GAs may be sensitive to a synthetic lethality approach with ATR inhibitors, with or without the addition of immune checkpoint inhibitors." (PMID 37821580, 2023). "Therefore, ATF2 could not further exert its tumor suppressive effect on the ATR-Chk1 complex, resulting in drug resistance." (PMID 37237279, 2023). "Moreover, data from 50 CRC patients showed ATR and CHK1 expression significantly increased in the tumor, compared to adjacent mucosa, and ATR expression has significantly increased in the late stages (III and IV), thus ATR and CHK1 appear to be important for tumor progression." (PMID 34201502, 2021). "Combining an ATR inhibitor (ATRi) with an ICI, thereby targeting an essential regulator of cell cycle checkpoints in addition to immune checkpoint pathway blockade, may synergistically activate anti-tumor immunity while minimizing the toxicity of combined therapies." (PMID 34298632, 2021). "Additionally, the proposed involvement of DNA-PKcs in the RSR13–15 also suggests that DNA-PK inhibitors could be useful in targeting tumours with high levels of replication stress, either as a single agent or in combination with other agents that modulate the RSR, such as ATR inhibitor AZD6738." (PMID 31699977, 2019). "This is achieved through stabilization of the replisome, without triggering the ATR pathway, and provides cells with a proliferative advantage under RS, promoting replication fork progression without activating checkpoint responses, which could be detrimental to tumor growth (bottom)." (PMID 41009395, 2025). "The authors reported that to achieve increased cytotoxic T cells in the tumor-draining lymph node (DLN), radiation therapy or immune checkpoint inhibition must be followed by a short ATR inhibition rather than a prolonged one." (PMID 38474014, 2024). "The mRNA expression levels of KRAS, ATR, CHEK1 genes in EC tissue samples from both groups with and without recurrence were independent of the depth of tumor invasion into the myometrium." (PMID 38669256, 2024). "The study showed that the ATR inhibitor AZD6738, and CHK1 inhibitor MK8776 suppressed PDX tumor growth in monotherapy, however there was no tumor regression observed." (PMID 35359749, 2022). "While ablation of the ATR-Chk1 axis results in cerebellar hypoplasia in non-tumor models, downregulation during SHH tumor development leads to extensive chromosomal abnormalities and abrogation of tumor development." (PMID 35747808, 2022). "Similar to ATR blockage, AGT silencing did not influence cell proliferation in vitro as detected by MTT assay and tumor growth in our immunodeficient mouse model (NOD/SCID mice)." (PMID 30208943, 2018).
tumor (continued). "Although one report with another ATR inhibitor using normal cells irradiated with high LET radiation was recently published, no information with VE-821 using carbon ion irradiated tumor cells is available." (PMID 26286029, 2015). "Otherwise, RT causes the release of irradiated tumor-cell-derived microparticles, which induce double-strand breaks (DSBs) and activate the ATM/ATR/CHK1 and the downstream JAK-STAT signaling pathways, leading to the upregulation of MHC-I in non-irradiated tumor cells." (PMID 40565309, 2025). "This specificity explains why these agents fail to exert efficacy in most solid tumors—without pre-existing DDR dependency, the untargeted non-DDR functions of ATR cannot be exploited to induce tumor cell death, and redundant DDR networks further compensate for ATR inhibition." (PMID 41409249, 2025). "Moreover, protein expression analysis indicated that although ATR is not differentially expressed in PDAC, tumor cells exhibit significantly higher CHEK1 levels than normal tissue." (PMID 39838187, 2025). "Thus, siPOLA1-mediated sensitization to ATR and CHK1 inhibitors is not a cell line-specific phenomenon of DLD-1 cells but can be generalized to a panel of cell lines of different tumor entities." (PMID 39128273, 2024). "Furthermore, the levels of ATR and CHEK1 mRNA were upregulated in tumor tissues compared to non-tumor tissues in the TCGA database (n = 50) and the GSE14520 cohort (n = 213)." (PMID 34663432, 2021). "We did not examine the effect of the combination of the ATR inhibitor and the ATM inhibitor, but adding both VE822 and KU60019 may more strongly enhance the anti-tumor effect of irradiation." (PMID 31805725, 2019). "Importantly, we also found that in low-grade NSCLC, increased expression of Claspin, Timeless, and CHK1 (but not ATR, RAD9, and RAD17), correlates with the aggressiveness of the tumor." (PMID 30796221, 2019). "Importantly, ATR and CHK1 inhibitors displayed a selective toxicity for SCLC tumor cells, but not for NSCLC tumor cells." (PMID 30060526, 2018). "Although the absence of a clear tumor regrowth in RT-treated conditions of the HPV-negative xenografts hampers the possibility to assess the tumor growth delay, a limited but significant reduction in tumor volumes could be seen in xenografts treated with the combination of ATR inhibitor and RT." (PMID 33546122, 2021).
infection (68 papers, 2008 to 2026). The state of being infected such as from the introduction of a foreign agent such as serum, vaccine, antigenic substance or organism. "In a small pilot study, looking specifically at DDR pathways, it was observed that infection of Vero E6 cells with SARS-CoV-2 causes activation of the ATR pathway, seen as increased phosphorylation of Chk1 on S280 and H2AX on S139." (PMID 37948194, 2023). "ATR has also been reported to promote replication, but another study reported that infection causes the aberrant localization of this arm of the HR pathway." (PMID 33563816, 2021). "When both ATM and ATR were deficient, the efficiency of dl366* infection was increased by 271-fold (ln(fold) = 6) and E4orf4 further increased replication efficiency by close to 3.3-fold (ln(fold) = 1.11)." (PMID 26867009, 2016). "ATM and ATR deficiency as well as E4orf4 expression enhance infection efficiency." (PMID 26867009, 2016). "To test whether this reduction of viral DNA replication in ATR-deficient cells was due to inefficient infection or trafficking to the nucleus, we quantified the amount of viral DNA in the nucleus very early in infection." (PMID 26817608, 2016). "To determine whether ATR molecules associate with the MVM genome during infection, we performed chromatin immunoprecipitation assays on nuclear extracts containing the viral genomes that we have recently developed to remove the secondary effects of host-associated cellular DDR sites." (PMID 37376543, 2023). "This leads to suppression of the ATR-mediated DDR pathways during MVM infection, likely exacerbating host genome instability." (PMID 40284937, 2025). "ATR is inhibited by HSV-1 ICP0 protein via the mislocalization of the ATR interacting protein during infection." (PMID 38140525, 2023). "This is further supported by decreased levels of NS1 and viral genome later in infection in the presence of the ATR inhibitor." (PMID 37376543, 2023). "While relocalization was only attenuated during early infection by inhibition of ATR, APAR body formation was still impacted and correlated with decreased overall virus replication." (PMID 37376543, 2023). "Alternatively, it is possible that ATR inactivation at the late stages of infection is a mechanism evolved by parvoviruses to evade integration into the host genome." (PMID 37376543, 2023). "HBoV1 infection initiates a DDR with activation of all 3 phosphatidylinositol 3-kinase–related kinases (PI3KKs), including ATM (ataxia telangiectasia mutated), ATR (ATM and RAD3 related), and DNA-PKcs (DNA-dependent protein kinase catalytic subunit)." (PMID 36719192, 2023). "ATR is activated through recognition of replicative stress during infection where it then induces DNA repair, cell cycle checkpoints, or apoptosis." (PMID 38140525, 2023). "Infection of U2-OS cells with UV-inactivated AAV2 initiated a DDR that involved activation of ATR and Chk1 kinases." (PMID 36719192, 2023). "These assays qualitatively suggested that ATR signaling is required for initial localization of NS1 to cellular DDR sites during infection." (PMID 37376543, 2023). "In particular, in a recent study examining DDR activation in EBV-exposed B cells, ATR/Chk1, but not ATM/Chk2 pathway, was activated, while specific targeting of ATR was able to suppress B cell aberrant function upon the infection." (PMID 36306362, 2022). "At increasing doses (0, 2, 4, 8, and 16 μM), the ATR inhibitor inhibited the upregulation of γ-H2AX induced by infection with EVA71; importantly, the ATR inhibitor also inhibited the expression of viral protein VP1." (PMID 35067196, 2022). "More ATR was coimmunoprecipitated with TopBP1 when TopBP1 levels were increased by Ad-TopBP1 infection from an MOI of 100 to 200, coinciding with the increased Chk1 phosphorylation." (PMID 33556369, 2021).
infection (continued). "Upon infection, H2AX and RPA32 are phosphorylated, and the signals are passed through phosphoinositide 3-kinases ATM (Ataxia telangiectasia mutated), ATR (ATM- and RAD3-related), and DNA-PKcs (DNA-dependent protein kinase catalytic subunit), respectively." (PMID 34220786, 2021). "In response to genotoxic stress, the northern corn leaf blight pathogen Setosphaeria turcica activates an ATR‐dependent pathway to suppress appressorium‐mediated infection and induces melanin‐related self‐protection." (PMID 31912966, 2020). "The Ad5 E4orf4 protein was also shown to inhibit the ATM and ATR signaling pathways that were activated during infection with an E4-mutant Ad, and it required its major partner, PP2A, for this function." (PMID 32906746, 2020). "We propose that certain phytopathogenic fungi activate self‐protection responses by increasing ATR‐dependent melanin production and inhibiting appressorium‐mediated infection as specific responses separate from conserved mechanisms." (PMID 31912966, 2020). "During infection with Ad3, Ad4, Ad7, and Ad11, ATR was activated, resulting in phosphorylation of Chk1." (PMID 32906746, 2020). "Infection of HeLa cells with colibactin-producing E. coli induces an ATR-dependent replication stress response." (PMID 29559578, 2018). "Western blot analyses showed that both ATM and ATR were phosphorylated following infection with pks+E. coli or after MMC treatment." (PMID 29559578, 2018). "Viral protein R (Vpr) is an accessory protein of HIV-1, which is potentially involved in the infection of macrophages and the induction of the ataxia-telangiectasia and Rad3-related protein (ATR)-mediated DNA damage response (DDR)." (PMID 29338752, 2018). "We find that vaccinia virus induces cytoplasmic activation of ATR early during infection, before genome uncoating, which is unexpected because ATR plays a fundamental nuclear role in maintaining host genome integrity." (PMID 28467896, 2017). "This induction, which is E1-dependent, suggests that replication stress caused by the initial amplification of viral genomes during the establishment-phase of infection activates an ATR response in cells." (PMID 28820495, 2017). "In this report, infection by JCV or transient transfection with a T-Ag expression plasmid resulted in activation of ATM and ATR causing cells to accumulate in the G2 phase of the cell cycle." (PMID 28202068, 2017). "First, we assessed the level of apoptosis induced by a selective ATR inhibitor (ATRi), VE-821,39 during the hyper-proliferative period early after infection." (PMID 28604764, 2017). "We have demonstrated that the related kinase ATR acts to promote virus replication as part of an infection-induced cytoplasmic ATR/ATM-dependent response." (PMID 28467896, 2017). "Vaccinia-induced phosphorylation of Chk1 and Chk2 further established that infection activates the ATR and ATM pathways." (PMID 28467896, 2017). "Using specific ATM and ATR inhibitors to target viral replication, particularly genome amplification in differentiated cells, as the loss of FA-dependent episomal maintenance could lead to increased rates of integration, may reduce the cells ability to support successful infection." (PMID 28820495, 2017). "The effect on checkpoint kinase 1 (Chk1) phosphorylation, an ATR substrate, in response to infection with different virus serotypes was investigated." (PMID 28791251, 2017). "Biochemical fractionation also established that RPA and ATR, as well as Ku70, part of the DNA-PK vaccinia DNA sensor complex, become significantly enriched in the cytoplasm during infection." (PMID 28467896, 2017). "We identified for the first time that EBV infection of TBCs induces a period of hyperproliferation 48-96 hours post infection characterized by the activation of ataxia telangiectasia and Rad3-releated (ATR) and checkpoint kinase-1 (Chk1)." (PMID 28031537, 2017).
infection (continued). "Inhibition of the DDR regulators ATM and ATR, as well as expression of E4orf4, enhances infection efficiency." (PMID 26867009, 2016). "The subsequent induction of cell cycle checkpoints and activation of ATM/ATR/DNAPKcs pathways have been reported to accompany infection by a number of different viruses." (PMID 24859341, 2014). "Inhibition of ATR during any phase of infection compromised cell cycle arrest as indicated by an increased percentage of cells in G1 phase and a decreased percentage of cells in S phase." (PMID 25474690, 2014). "The role of ATR kinase activity in infection was directly examined by treating SV40-infected BSC40 cells with a specific small molecule inhibitor of ATR, VE-821 (ATRi), during three different time windows of infection." (PMID 23592994, 2013). "HPVs induce the ATR response in foci during the initial amplification phase of infection but expression and nuclear localization of the E1 protein must be tightly regulated to allow persistent viral replication and cell division." (PMID 24278023, 2013). "ATR levels remained relatively unchanged during infection; however, both Chk1-pS317 and Chk1-pS296 increased starting at 2 dpi." (PMID 22952448, 2012). "We assessed the involvement of ATM and ATR during infection using small interfering RNA (siRNA) knockdowns." (PMID 22952448, 2012). "Recent work from our laboratory indicates that RVFV infection causes opposing activation of ATM and ATR pathways, where ATM and chk2 phosphorylation are up-regulated at 24 hours post-infection, whereas ATR phosphorylation is down-regulated." (PMID 22574148, 2012). "Treatment with UCN-01 also resulted in a partial decrease in viral DNA replication and a severe reduction in viral titer, consistent with ATR/Chk1 pathway being required for BKPyV productive infection." (PMID 22952448, 2012). "In normal primary fibroblasts, the presence of viral DNA in NBS1, ATM, and ATR immunoprecipitates was first detected 12 hrs post-infection." (PMID 18211700, 2008). "Importantly, treatment with caffeine or ATM/ATR-specific inhibitors reduced Vpr-enhanced mCherry expression to that of control infection." (PMID 39975144, 2025). "Interestingly, when ATR was activated prior to infection, a small but significant two-fold reduction was observed in recombination frequencies between coinfecting genomes." (PMID 38932138, 2024). "We found that induction of DDR occurred following rAAV2.5T infection, which was characterized by the phosphorylation of replication protein A32 (RPA32) and histone variant H2AX (H2A histone family member X), as well as all three PIKKs: ATM, ATR, and DNA-PKcs." (PMID 37841417, 2023). "It has been reported that infection of UV-inactivated AAV induced an ATR-dependent DDR." (PMID 36719192, 2023). "Similarly, infection with large DNA viruses such as Herpes Simplex Virus 1 (HSV1) induces activation of ATR and CHK1 that colocalize with ICP4 and ICP0 proteins in viral replication centers in the nucleus." (PMID 37253065, 2023). "EVA71 might induce DNA single-strand breaks to activate the ATR pathway which is responsible for the formation of γ-H2AX after EVA71 infection whereas the activation of ATM or DNA-PK might be lowered after EVA71 infection." (PMID 35067196, 2022). "While both ATM and the related ATR DDR kinase appear to be activated by infection, it is unclear whether they affect replication." (PMID 33563816, 2021). "We propose that in response to genotoxic stress, phytopathogenic fungi including S. turcica activate an ATR‐dependent pathway to suppress appressorium‐mediated infection and induce melanin‐related self‐protection in addition to conserved responses in eukaryotes." (PMID 31912966, 2020). "This was similar in ex vivo human whole blood infection using ATR inhibitors." (PMID 31274379, 2019).